IL6 (interleukin 6)
Diseases named in the same sentence as IL6 in open-access papers (continued):
Sharing a sentence is not in itself a finding about the gene and the disease.
Obesity (continued). "Research indicates that the inflammatory response associated with obesity correlates with changes in plasma levels of C-reactive protein (CRP), interleukin-6 (IL-6), and other inflammatory biomarkers." (PMID 41590696, 2026). "Individuals with obesity consistently show elevated circulating IL-6, TNF-α, and C-reactive protein (CRP)." (PMID 41543809, 2026). "In inflammatory settings, sinensetin attenuates NF-κB activation, lowers pro-inflammatory cytokines (e.g., TNF-α, IL-6), and enhances antioxidant defenses, supporting its reported antioxidant, anti-bacterial, anti-viral, and anti-obesity properties." (PMID 41597185, 2026). "Although the number of studies focusing on metabolomics in the context of hypertension in children and adolescents with obesity is limited, the most important adipokines and cytokines affecting the cardiovascular system include adiponectin, leptin, and IL-6." (PMID 41596212, 2026). "IL-6 is involved in renal inflammation and injury in cardiovascular disease including obesity, and macrophages can produce IL-6." (PMID 41463113, 2025). "The adipose tissue in obesity secreted pro-inflammatory cytokines, such as IL-1β and IL-6, while simultaneously impairing the secretion of anti-inflammatory adipokines like adiponectin." (PMID 41009007, 2025). "Prior cross-sectional studies demonstrated possible connections between obesity, IL-6, and asthma severity." (PMID 39714726, 2025). "Obesity increases the secretion of IL-6 and other pro-inflammatory cytokines from macrophages, Leydig cells, and Sertoli cells in the testis, further exacerbating testicular inflammation." (PMID 40564033, 2025). "miR-146a displayed context-specific changes, where it is increased in obesity, but reduced or mixed in prediabetes, suggesting stage-dependent modulation of inflammatory signaling through IL-6 and TNFα." (PMID 41400625, 2025). "Obesity is associated with a chronic low-grade inflammation, and inflammatory markers related to obesity include TNF-α, IL-6 [24,26,27,], and the anti-inflammatory cytokine IL-10." (PMID 40125475, 2025). "Since adipocytes and preadipocytes are identified as reservoirs for proinflammatory cytokines, including TNF-α, IL-1, and IL-6, obesity is a chronic inflammatory condition." (PMID 40566527, 2025). "Curcumin reduces the production of pro-inflammatory cytokines, such as TNF-α and IL-6, which are central to the pathophysiology of diabetes and obesity." (PMID 40918536, 2025). "Depression and obesity are highly comorbid and frequently co-occur with inflammation mediated by proinflammatory cytokines such as IL-6 and TNF-α." (PMID 40698360, 2025). "Inflammatory cytokines, such as tumor necrosis factor (TNF) and interleukin‐6 (IL‐6), can disrupt the normal balance of energy metabolism and lead to insulin resistance, which can further promote weight gain and obesity." (PMID 39652453, 2025). "However, IL-6 was not only associated with acute inflammation but could also be found in elevation in various acute and chronic conditions, including trauma, surgery, malignancy, cardiovascular diseases, obesity, and other metabolic diseases." (PMID 40217808, 2025). "Obesity promotes systemic inflammation through elevated cytokines such as interleukin-6 (IL-6) and tumor necrosis factor-alpha (TNF-α), leading to airway inflammation and hyperresponsiveness." (PMID 41244254, 2025). "More studies are necessary to understand this paradoxal relationship of IL-6 and its impact on obesity management." (PMID 41141350, 2025). "This suggests a potential mechanism for the elevated levels of IL‐6 commonly observed in severe COVID‐19 patients, particularly people living with obesity." (PMID 40265287, 2025). "Significant differences were observed in IL-6, IL-10, IL-13, 25-(OH) D3 levels, and leptin among children with asthma combined with obesity/overweight and those with asthma or obesity/overweight alone." (PMID 40083433, 2025).
Obesity (continued). "HsCRP and IL-6 lack specificity for coronary artery disease (CAD), as they reflect systemic inflammation influenced by infections, obesity, or other conditions, limiting their diagnostic accuracy for isolated coronary tree inflammation." (PMID 41511355, 2025). "Metabolic dysregulation, particularly in the context of obesity, compounds these effects by fostering a pro-inflammatory milieu characterized by increased levels of leptin, adiponectin, interleukin-6 (IL-6), and TNF-α." (PMID 40243679, 2025). "Chronic inflammation associated with obesity elevates pro-inflammatory cytokines like TNF-alpha and IL-6, exacerbating oxidative stress and DNA damage in sperm cells." (PMID 40008399, 2025). "In conclusion, this study highlights IL-6, Ca2+, sAA, MUC5B and cortisol as a potential salivary biomarker-combination associated with obesity." (PMID 41584074, 2025). "Interleukin‐6 (IL‐6) and 8 (IL‐8) showed higher expression in the AT of obese subjects and are involved in the recruitment of immune cells and in the pathogenesis of obesity and insulin resistance." (PMID 40377300, 2025). "Separate models were also analyzed (adjusted for other significant covariates) to determine the impact of obesity and asthma on IL-6 levels." (PMID 39714726, 2025). "Future research should explore anti-IL-6 therapies for specific phenotypes, such as obesity-related asthma." (PMID 39714726, 2025). "ELISA findings revealed that the levels of interleukin‐6 receptor subunit beta (gp130), oncostatin‐M (OSM), and IL‐6 in serum and hippocampus decreased in obesity, whereas they increased in AD, aligning with the results of the MR Analysis." (PMID 40958408, 2025). "Adipose tissue in obesity releases adipokines (like IL-6, leptin, TNF-α) that sustain systemic inflammation and can alter gut microbiota composition." (PMID 41374093, 2025). "Contraction-induced myokines (e.g., IL-6) can further augment insulin signaling and exert anti-inflammatory effects, which is pertinent for individuals with obesity who commonly exhibit low-grade inflammation and insulin resistance." (PMID 41356824, 2025). "Notably, we found that IL-6 exhibited a significant concentration difference between the serum of healthy and obesity children, suggesting the IL-6 may play a key role in the inflammatory response associated with obesity." (PMID 40519917, 2025). "Leptin, which is notoriously abundant in obesity, triggers the expression of a host of pro-inflammatory and pro-tumorigenic cytokines, notably IL-1, IL-6, and TNF-α within macrophages." (PMID 40040878, 2025). "Inflammation is also present in cases of obesity in childhood and adolescence, especially caused by cytokines such as MCP-1, IL-6, TNF-α and IL-1β." (PMID 40002337, 2025). "Obesity is often characterised by inflammation, as adipose tissue stimulates the release of inflammatory mediators such as tumour necrosis factor-α and interleukin-6." (PMID 41300410, 2025). "Adipose tissue expansion in obesity triggers chronic low-grade inflammation, characterized by an increased production of pro-inflammatory cytokines, including IL-6, IL-1, IL-8, and TNF-α, primarily by infiltrating macrophages." (PMID 40298814, 2025). "This systematic review and meta‐analysis were performed to analyze the effect of achieving weight loss through dietary interventions on serum IL‐6 and TNF‐α in adults with obesity with at least 12 months' follow‐up." (PMID 40090867, 2025). "The subgroup analysis on BMI revealed that overweight and obesity are associated with a reduced response to the most favorable effects of the supplementation, particularly in terms of suppressing CRP and IL-6 markers." (PMID 41022286, 2025). "We did not observe significant differences in the values of beta-defensin 2 (p = 0.936), presepsin (p = 0.175), IL-6 (p = 0.341), and ferritin (p = 0.237) between the obesity group and the control/overweight group." (PMID 40868054, 2025).
Obesity (continued). "Adipose tissue, primarily abdominal fat, is inflamed in the obese state and contributes to the increased systemic levels of IL-6 observed in obesity." (PMID 40637163, 2025). "At 12 and 28 GW, women with obesity had higher IL-6 concentrations compared with normal weight women (12 GW 2169 vs 1371 fg/mL, P = 0.004; 28 GW 2251 vs 1460 fg/mL, P = 0.021 in obesity and normal weight, respectively)." (PMID 40886951, 2025). "During inflammatory processes, such as obesity, the excessive production of IL-6 can lead to chronic activation of the trans-signaling pathway, thereby favoring insulin resistance and contributing to the development of metabolic diseases." (PMID 40647244, 2025). "Chronic low-grade inflammation is a hallmark of prediabetes and obesity, typically characterized by elevated levels of hs-CRP, IL-6, and TNF-α." (PMID 41228432, 2025). "Our results conflict with studies reporting positive correlations between obesity and IL-6/TNF-α in schizophrenia." (PMID 40791199, 2025). "The elevated levels of pro-inflammatory cytokines, such as TNF-α, IL-1, IL-6, and LIGHT, associated with obesity promote osteoclastogenesis and impair bone formation." (PMID 39940349, 2025). "The common mechanisms that bromelain can interfere with are the reduction in pro-inflammatory cytokines (TNF-α, IL-1β, IL-6), which are excessively produced both in obesity (by macrophages in adipose tissue) and in other inflammatory conditions." (PMID 40943267, 2025). "The combined alterations in IL-6, Ca2+, sAA, MUC5B and cortisol indicate a potential salivary biomarker pattern associated with obesity, underscoring the value of a multi-biomarker strategy for metabolic risk profiling." (PMID 41584074, 2025). "In adolescentes with obesity, high concentrations of IL-6 have been a reflection of a proinflammatory and prothrombotic state, being strongly associated with the presence of insulin resistance." (PMID 40717997, 2025). "IL-6 systemically regulates body weight and lipid metabolism, and it is also involved in obesity, as well as IR." (PMID 40244195, 2025). "The expansion of adipose tissue caused by obesity is linked to an increased production of pro-inflammatory cytokines (including TNF-α and IL-6), impairing BBB function, increasing microglia activation, and elevating CNS inflammation." (PMID 41515969, 2025). "Mice fed a high-fat diet exhibit obesity-related systemic insulin resistance and elevated circulating IL-6 levels, while blockade of excessive IL-6 signaling improves systemic insulin sensitivity illustrated by upregulated skeletal muscle glucose uptake." (PMID 40171198, 2025). "HFD causes obesity, increases inflammatory cytokines (e.g., TNF-α, IL-6), and promotes lipid accumulation in the liver, which impairs insulin receptor function." (PMID 40689212, 2025). "As compared with individuals with normal weight, people with obesity exhibit higher postprandial glucose, insulin, TG, and inflammatory markers such as IL-6, TNF-α, and CRP." (PMID 41301434, 2025). "Dense stroma‐induced hypoxia stabilizes HIF‐1α and, in concert with obesity‐related cytokines (such as IL‐6, TNF‐α, and leptin), activates the JAK/STAT3 pathway, upregulates PD‐1/PD‐L1 expression, and suppresses antigen presentation." (PMID 41267926, 2025). "Biomarkers such as C-reactive protein, IL-6 and TNF can indicate the presence of systemic inflammation associated with obesity." (PMID 40553147, 2025). "As an acute-phase reactant to inflammation and infection, C-reactive protein (CRP) is associated with obesity along with inflammatory mediators such as TNF-α and IL-6." (PMID 40939575, 2025). "Cytokines like TNF-α, IL-1β, and IL-6 not only fuel tumor growth in obesity-afflicted mouse models but also parallelly increase in obese women, closely correlating with the onset and progression of breast tumors." (PMID 40040878, 2025). "CRP and IL-6 are considered inflammatory biomarkers to assess the presence and severity of low-grade inflammation in obesity." (PMID 40565915, 2025).
Obesity (continued). "Studies have shown that obesity induces baseline elevation of proinflammatory cytokines such as IL-6 and TNF-α in the brain, with heightened levels in the cortex and hippocampus." (PMID 40216734, 2025). "Obesity has been found to cause localized decreases in PO2, resulting in elevated levels of leptin, IL-6, vascular endothelial growth factor (VEGF), glucose transporter 1 (GLUT1), and PAI-1." (PMID 40871683, 2025). "The TNF-α and IL-6 levels were high in participants with obesity, and diabetes with obesity, compared to control group." (PMID 40095937, 2025). "Inflammatory markers such as C-reactive protein (CRP) and IL-6 are elevated in women with overweight/obesity." (PMID 40886951, 2025). "Obesity is accompanied by chronic systemic inflammation and leads to an increase of IL-6 and TNF-α in plasma." (PMID 41224847, 2025). "Under ME conditions in vitro, we detected in BC cells significantly increased expression of TNFα, CCL2, IL-6 and human IL-8, well-known TLR-controlled cytokines, tightly implicated in breast tumorigenesis and the obesity-cancer link." (PMID 40868123, 2025). "Obesity contributes via chronic low-grade inflammation and adipokine dysregulation, as studies reported elevated interleukin-6 levels in obese surgical patients." (PMID 40720484, 2025). "Obesity and depression share a state of chronic low-grade inflammation, sustained by an overproduction of proinflammatory cytokines such as IL-1β, IL-6, and TNF-α." (PMID 41373743, 2025). "Chronic inflammation is linked to obesity, generating proinflammatory cytokines such as TNF-α, IL-6, IL-1β, and IL-18 that activate NF-kB." (PMID 40703753, 2025). "Obesity, a major risk factor, is associated with elevated pro-inflammatory markers (TNF-α, IL-6) and reduced anti-inflammatory IL-10 and adiponectin." (PMID 40941639, 2025). "The aim of the current letter is to study the effect of overweight and obesity on interleukin-6 levels in children and adolescents with asthma." (PMID 40696834, 2025). "Obesity‐associated inflammation, characterized by increased CRP, IL‐6, leptin, and TNF‐α, further exacerbates endometrial cancer progression by enhancing cancer cell invasion and inhibiting apoptosis." (PMID 40922069, 2025). "The results revealed that children with obesity or overweight exhibited a significant increase in salivary IL-6 levels, up to 4.5 times higher than their normal-weight counterparts, with only two overweight children showing normal IL-6 values." (PMID 40282897, 2025). "Myeloid-derived suppressor cells (MDSCs), expanded in obesity in response to elevated levels of IL-6 and other cytokines, contribute to this immune evasion by suppressing CD8+ T cell activity and further promoting M2 polarization." (PMID 41432903, 2025). "In individuals with obesity, pro-inflammatory cytokines such as interleukin-6 (IL-6), IL-1β, and tumor necrosis factor-α (TNF-α) can upregulate hepcidin, a central regulator of iron homeostasis." (PMID 41141252, 2025). "Obesity also contributes to the production of inflammatory molecules such as interleukin-6 (IL6) and tumor necrosis factor-α (TNFα), favoring the creation of an environment useful for MPNs’ progression." (PMID 40725771, 2025). "Perimenopausal women with overweight or obesity (BMI ≥ 25 kg/m2) showed significantly higher levels of glucose, insulin resistance indices, IL-6, and CRP, confirming the contribution of excess body weight to low-grade systemic inflammation." (PMID 40944273, 2025). "Compared to normal-weight subjects, M1-type adipose tissue macrophages are specifically present in patients with obesity and induce an inflammatory response by secreting pro-inflammatory adipokines such as interleukin- 6, TNF-α, and nitric oxide." (PMID 40099262, 2025). "Further, MP also rescued the obesity-induced hippocampal cellular damage and inhibited the overexpression of IL-6 in hippocampal tissues, indicating reduced neuroinflammation induced by the obesity." (PMID 40297338, 2025).
Obesity (continued). "Adipose tissue also produces a variety of adipokines and proinflammatory cytokines linked to obesity-associated male infertility, including leptin, adiponectin, resistin, ghrelin, TNF-alpha, IL-1β and IL-6." (PMID 40140188, 2025). "IL-6, a predictive marker of systemic inflammation and metabolic syndrome in obesity is also involved in the severity of asthma with obesity." (PMID 40589493, 2025). "First, visceral fat in obesity acts as an active endocrine organ, secreting various pro-inflammatory cytokines such as tumor necrosis factor-α, interleukin-6, and IL-1." (PMID 41465937, 2025). "Our findings indicate that higher IL-6 levels correlate with more severe asthma as assessed by lung function, especially among individuals with obesity." (PMID 39714726, 2025). "Quercetin also presents anti-inflammatory action in obesity-related inflammatory gut microbiota and modifies IL-6 levels in the serum of obese children." (PMID 40244195, 2025). "Studies have shown that abnormal lipid metabolism occurs in obesity‐related renal fibrosis due to the excessive production of inflammatory cytokines such as tumour necrosis factor and interleukin‐6 (IL‐6) in kidneys." (PMID 40079088, 2025). "Adipose expansion in obesity promotes dysregulated adipokine secretion and macrophage infiltration, leading to release of inflammatory mediators such as IL-6 and TNFα." (PMID 41400625, 2025). "In our cohort, individuals with obesity showed elevated plasma Ang II, heightened concentrations of IL-1β, IL-6, and TNF, and reduced IL-10, supporting the presence of a dysregulated inflammatory state exacerbated by viral infection." (PMID 41562075, 2025). "Another crucial pro‐inflammatory factor, IL‐6, has been found at increased concentrations in individuals affected by obesity." (PMID 39763022, 2025). "Obese adipocytes secrete pro-inflammatory cytokines such as tumor necrosis factor-α (TNF-α) and interleukin-6 (IL-6), which activate the “obesity–inflammation–aromatase axis”." (PMID 41157306, 2025). "There is abundant evidence that circulating levels of inflammatory markers, including high-sensitivity C-reactive protein (hs-CRP), interleukin-6 (IL-6), and ferritin, are significantly higher in people with obesity compared to peers of normal weight." (PMID 40868054, 2025). "Crucially, this exercise-induced IL-6 exhibits an anti-inflammatory profile that is fundamentally distinct from the chronically elevated IL-6 observed in aging and obesity." (PMID 41514897, 2025). "Our previous clinical trial on individuals with obesity demonstrated that NAC supplementation significantly reduced serum IL-6 and CRP levels while downregulating p16 and IL6 gene expression in adipose tissue." (PMID 40421021, 2025). "Inflammatory cytokines such as TNF-α, IL-1β, and IL-6 can reduce insulin sensitivity and promote obesity." (PMID 40298814, 2025). "Seric IL-6 level was significantly higher in patients with obesity and showed a highly significant inverse relationship with insulin sensitivity, with a correlation coefficient of −0.71." (PMID 41155523, 2025). "In the pathogenesis of T2DM and obesity, inflammatory factors, particularly IL-6 and TNF-α, play a crucial role." (PMID 40842495, 2025). "In obesity, IL-6 elevation initially drives M1-like adipose tissue macrophages (ATMs), contributing to insulin resistance, but sustained IL-6/STAT3 activation favors M2-like phenotypes with immunosuppressive features." (PMID 41310829, 2025). "GATA3 upregulation in the VAT of subjects with obesity increased IL-6 secretion, which in turn activated macrophage infiltration by upregulating monocyte chemoattractant protein-1 (MCP-1, encoded by the CCL2 gene)." (PMID 40423250, 2025). "In obesity, a persistent state of chronic inflammation is established, resulting in the secretion of pro-inflammatory cytokines such as IL-6, IL-1β, and TNF-α." (PMID 40565082, 2025).